ZNF225 (zinc finger protein 225)
Description:
May be involved in transcriptional regulation.
Tractability: PROTAC: UniProt records ubiquitination sites on it; ubiquitination databases record sites on it.
Gene: Protein-coding gene on chromosome 19 (44,112,181 to 44,135,055, forward strand). Ensembl gene ENSG00000256294.
Subcellular location: Nucleus
Subcellular location (Human Protein Atlas): Nucleoplasm
Pathways (Reactome):
Gene expression (Transcription): Generic Transcription Pathway
Gene Ontology:
Molecular function: protein binding; transcription cis-regulatory region binding; DNA-binding transcription repressor activity, RNA polymerase II-specific; sequence-specific DNA binding
Biological process: regulation of transcription by RNA polymerase II; negative regulation of transcription by RNA polymerase II; regulation of DNA-templated transcription
Cellular component: nucleus; nucleoplasm
Genetic constraint (gnomAD): Loss-of-function variants: 7 observed, 13.37 expected, observed/expected ratio (o/e) 0.52, 90% interval 0.3 to 0.98. The upper end of that interval is the gene's LOEUF score, 0.98, which puts it in group 4 of 6, group 1 being the genes least tolerant of losing a copy. Missense variants: 763 observed, 890.67 expected, observed/expected ratio (o/e) 0.86, 90% interval 0.81 to 0.91. Synonymous variants: 271 observed, 297.42 expected, observed/expected ratio (o/e) 0.91, 90% interval 0.82 to 1.01.
Homologues: Paralogues in human: ZNF224 (74% identical), ZNF284 (65% identical), ZNF221 (63% identical), ZNF235 (40% identical), ZNF227 (39% identical), ZNF229 (38% identical), ZNF226 (38% identical), ZNF33B (37% identical), ZNF112 (37% identical), ZNF595 (36% identical), ZNF726 (36% identical), ZNF841 (36% identical), and 164 more.
Diseases named in the same sentence as ZNF225 in open-access papers:
ZNF225 is named in the same sentence as 4 diseases in open-access papers, as found by Europe PMC text mining. Sharing a sentence is not in itself a finding about the gene and the disease. The quoted sentences say what the papers report.
cervical cancer (1 paper, 2021). A primary or metastatic malignant neoplasm involving the cervix. "The remaining 10 genes (i.e., YJEFN3, SPATA5L1, C5orf55, PPM1A, IMMP1L, ZNF330, PPIP5K2, ESCO2, FICD, and ZNF225) are not directly reported to be related to the survival risk of cervical cancer in previous literature." (PMID 34149809, 2021).
esophageal cancer (1 paper, 2023). A primary or metastatic malignant neoplasm involving the esophagus. "Results indicate that ZNF91, and ZNF586 were upregulated in esophageal cancer tissue than adjacent tissue, whereas ZNF502, ZNF865, ZNF106, and ZNF225 was downregulated." (PMID 37013470, 2023).
hepatocellular carcinoma (1 paper, 2023). A malignant tumor that arises from hepatocytes. "Little research has been done on the role of ZNF225 in ESCA, and a few evidences suggest ZNF225 inhibits autophagy and promotes apoptosis of hepatocellular carcinoma cells." (PMID 37013470, 2023).
tumor (2 papers, 2015 to 2024). "The identified somatic variants in the transcriptional activators ZNF225 and MED23 seem to be associated with the deregulation of gene expression and play a role in tumor pathogenesis and potential progression (particularly MED23)." (PMID 38721148, 2024). "EGR1 (ZNF225, KROX24, AT225) is a highly regulated putative tumor suppressor gene that regulates the transcription of genes involved in multiple cellular processes such as inflammation and apoptosis." (PMID 25710169, 2015).